FOXP3 (forkhead box P3)
Diseases named in the same sentence as FOXP3 in open-access papers (continued):
Sharing a sentence is not in itself a finding about the gene and the disease.
cancer (continued). "As demonstrated by FACS 3.8% to 6.1% of the cancer cells indeed expressed Foxp3." (PMID 23382847, 2013). "Current studies have rarely reported concrete relevance for FOXP3 expression in tumors; the transcript types and biological significance of FOXP3 in cancer remains unclear." (PMID 23759077, 2013). "FOXP3 appears to be a multifaceted factor with seemingly opposite functions in cancer biology." (PMID 23888189, 2012). "It has been shown that the combined assessment of CD127 and FoxP3 expression may be superior to CD25/FoxP3 for an accurate identification of Treg cells in patients with cancer, including MM." (PMID 22567028, 2012). "AJCC disease staging is based on histological evidence of infiltration and metastasis, it was, therefore, hypothesised that SPARC and FOXP3 expression may be associated with primary CRC disease stage and cancer specific survival." (PMID 21818290, 2011). "However, even the inclusion of FOXP3 assessment has been interpreted differentially when assessing frequencies of Treg cells in healthy individuals and cancer patients." (PMID 21904560, 2011). "However, high numbers of FoxP3+ cells detected by immunohistochemistry in inflamed skin and cancer tissue most likely represent regulatory T cells." (PMID 20727190, 2010). "In conclusion, successful cancer immunotherapy may depend on the ability to block upregulation of Foxp3 in effector CD4+ T cells and/or selectively inhibiting the expansion of a minor Treg subset." (PMID 21049016, 2010). "FOXP3Δ2Δ7 could play a role in regulating the function of the other FOXP3 isoforms and may be involved in cancer pathogenesis, as it is overexpressed by certain malignant cells." (PMID 19568423, 2009). "The Foxp3+/IDO+ group almost exclusively consisted of cancer patients with node positive disease." (PMID 19604349, 2009). "The proportion of Foxp3+ cells was higher in SLN of cancer patients than controls (19% v." (PMID 19604349, 2009). "As an alternative cancer immunotherapeutic strategy, small molecules targeting FoxP3 in Tregs could achieve higher effects than biologicals and macromolecules due to their ability to cross the cell membrane, their easier penetration into the TME, and their possible oral availability." (PMID 40034859, 2025). "Furthermore, as PD-1/PD-L1 and CTLA4 inhibitors have been extensively evaluated clinically in patients with many cancer types, combinations of FoxP3 regulators and ICIs may be possible to test where ICIs do not work optimally." (PMID 40034859, 2025). "Immune checkpoint inhibitors, such as those targeting CTLA‐4 and PD‐1, have demonstrated significant clinical responses in other cancers, and our study identifies high expression of Treg markers like FOXP3 and CTLA‐4 in HB, suggesting these may serve as important immunotherapeutic targets." (PMID 40099956, 2025). "Furthermore, there was an expression of FoxP3 in cancer cells, indicating that it may be involved in the malignant transformation of cancer cells." (PMID 39150932, 2024). "Furthermore, we examined the immunoreactivity of FoxP3-positive cells in cancer tissues." (PMID 39150932, 2024). "Therefore, to date, the significance of FOXP3 expressed in cancer remains under debate." (PMID 38041531, 2024). "This indicates that Foxp3 could be a highly attractive target in cancer immunotherapy." (PMID 39290699, 2024). "However, FoxP3 has recently been shown to be expressed in various cancer cells." (PMID 39150932, 2024). "A strong correlation (p < 0.05), between immunosuppressive CD4+CD25+FoxP3+ regulatory T cells and baseline sPD-L1 was observed in patients with unfavorable postoperative course of the disease, supporting the idea that these elements influence each other in cancer progression." (PMID 39055716, 2024). "Cancer cells themselves expressed FoxP3, which may lead to malignant transformation." (PMID 39150932, 2024).
cancer (continued). "Therefore, we speculate that PIK3C2A can transform Tregs into proinflammation cells which have anti-cancer-promoting utility by decreasing the expression of FOXP3." (PMID 37063922, 2023). "Furthermore, several immunosuppressive cells were identified to reprogram the metastatic ecosystem, including FOXP3+ regulatory T (Treg) cells, LAMP3+ tolerogenic DCs (tDCs), CCL18+ M2‐like macrophages, RGS5+ cancer‐associated fibroblasts, and LGALS1+ microglial cells." (PMID 36529697, 2023). "Interestingly, the enrichment of CD8+ T cells and much more aggregation of CD4+ T cells, CD49b+ NK cells were observed in CRC mice accepted with FMT, as well as reduced population of Foxp3+ Treg cells, F4/80+ macrophages, indicating the augmentation of anti-cancer efficacy." (PMID 37143538, 2023). "The mean value of Foxp3+ cells of the intratumoral, adjacent, and distant stroma was significantly higher in simple, solid than in complex carcinomas (p < 0.000) as well as than in simple tubular carcinomas (p = 0.01 for the intratumoral compartment, p = 0.000 for both adjacent and distant stroma)." (PMID 36766393, 2023). "In this study, the presence of FoxP3+ Tregs locally in head and neck cancer, particularly in OSCC, was evaluated using immunohistochemical staining, and the association with clinicopathological indices was clarified to elucidate some localized cancer immune responses." (PMID 34319010, 2022). "Given that CD4 + T cells, CD8 + T cells and immune suppression by CD4 + FOXP3 + regulatory T (Treg) cells represent two major factors impacting response to cancer immunotherapy, this finding suggests that the dysregulated autophagy pathways may affect the response of immunotherapy." (PMID 35550147, 2022). "Interestingly, FOXP3 expression was also detected in cancer cells, in 20% of the tumors." (PMID 36010856, 2022). "However, this association is not seen in all cancer types, as FoxP3+ T lymphocyte infiltrates have been associated with good prognosis in other cancers, such as head and neck cancers." (PMID 34440038, 2021). "In addition, pro-inflammatory Treg subpopulations such as IL-17-producing Tregs and Foxp3+RORγt+ Tregs may contribute to cancer development in IBD." (PMID 34884543, 2021). "Importantly, there is ample evidence that Helios-expressing Foxp3+ Tregs are relevant to various human disorders, including connective tissue diseases, infectious diseases, solid organ transplantation-related immunity, and cancer." (PMID 34257746, 2021). "In addition, the prognostic value of CD4+ T and FOXP3+ T cells requires further investigation due to protumoral and antitumoral functions that have been postulated for FOXP3 TILs’ (Tregs’) expression in different cancers." (PMID 34201050, 2021). "Immune escaping is a common feature of carcinomas and is achieved by multiple mechanisms, one of which is the negative modulation of CD4+ and CD8+ T effector (Teff) lymphocytes, caused by the activity of forkhead box protein 3 (FOXP3)-positive T regulatory cells (Treg)." (PMID 34539667, 2021). "However, it may have been a major confounding factor in previous studies showing conflicting correlations with prognosis for CD4+FOXP3+ T cells in cancer." (PMID 32377339, 2020). "FOXP3 has a crucial role in the development and function of Tregs, and excessive Tregs could prevent the immune system from destroying cancer cells and promote cancer progression." (PMID 32463792, 2020). "Also, it has been shown that, cancer cells express FOXP3, suggesting that FOXP3 may have some roles in cancer progression." (PMID 31653148, 2019). "Therefore interfering with the regulation of Foxp3 by AREG in cancer patients could lead to Foxp3 protein degradation in Treg cells and provide a potential novel therapeutic target for cancer treatment." (PMID 29102676, 2018).
cancer (continued). "We also found the higher numbers of non-synonymous mutations were correlated with higher ratio of an immune suppressive marker FOXP3/TCRB along with lower CD8/FOXP3 ratio, which might reflect counter-immunosuppressive mechanisms to protect cancer cells from a host immure attack." (PMID 28977923, 2017). "In fact, the CD4+ CD25+ Foxp3+ Tregs subpopulation may exert a critical role in cancer promotion." (PMID 29375559, 2017). "FoxP3+ T regulatory cells (Tregs), other immune suppressive cell, accumulate in tumors and increase in the peripheral blood of cancer patients, and the increased Tregs in tumors frequency has been shown to be a marker of poor prognosis in various types of cancers." (PMID 29221113, 2017). "Thus, it seems that the exact function of FOXP3 acts in a cancer type-specific manner." (PMID 28903735, 2017). "Whether Foxp3-positive cancer cells are relevant to recurrence is controversial." (PMID 27457382, 2016). "Moreover Tregs are involved in the inhibition of effector functions in both inflammation and cancer; it has been shown that the presence of CD4+CD25+FOXP3+ regulatory T cells in cancer tissues is associated with mechanisms of tumor immune escape and worse prognosis." (PMID 27323400, 2016). "However, less is known about the role of Foxp3 in the transcriptional regulation in cancer cells." (PMID 25779374, 2015). "However, the prognostic value of FoxP3+ Tregs varied significantly according to carcinoma sites." (PMID 26462617, 2015). "Healthy women participating in regular exercise had significantly lower percentage of circulating CD4+/CD25+/FOXP3 Tregs, compared with women that were more sedentary.Thus, exercise training during cancer treatment may help reduce the immunosuppressive effects of Tregs." (PMID 24312199, 2013). "However, the biological significance of Foxp3 expression in cancer cells of patients with CRC remains unknown." (PMID 23382847, 2013). "However, there are no relevant reports on the relationship between FOXP3 gene polymorphism and cancer." (PMID 23759077, 2013). "We detected a significant downregulation of CD127 mRNA expression in CD4+CD25high T cells from healthy donors (n = 5) as well as CLL patients (n = 5, P < 0.05) by quantitative PCR indicating that CD127 expression might also be used to specifically identify CD4+FOXP3+ Treg cells in cancer patients." (PMID 21904560, 2011). "Moreover, the percentage of FOXP3+ cells within the CD4+CD127low T-cell population was always higher than within the CD4+CD25high population, suggesting that previous data only assessing a CD4+CD25high phenotype have underestimated the absolute increase of FOXP3+ Treg cells in cancer patients." (PMID 21904560, 2011). "Collectively, our findings reveal that MCT4-mediated lactate uptake sustains Treg stability and function through Foxp3 lactylation, identifying MCT4 as a potential therapeutic target for modulating Treg activity in cancer." (PMID 42196594, 2026). "In a pan-cancer analysis (N = 2,023; 632 deaths), we observed that patients had longer OS with high intratumoral CD8+, PD-1+, CD8+PD-1+, or FOXP3+ cell counts compared with those with intermediate or low cell counts (all log-rank P < .0001)." (PMID 40906987, 2025). "Futurestudies should incorporate Treg-specific markers such as FOXP3 tofurther characterize the functional phenotype of CD25+ Tcells and confirm the suitability of Diatom-aAPCs for pro-inflammatoryapplications such as cancer immunotherapy." (PMID 40530806, 2025). "For PFS, biomarkers were detected in 10 cancer types, with CALR, CASP8, FOXP3, and LY96 consistently identified in at least three cancers." (PMID 41150760, 2025). "In tumors, we detected a higher abundance of proliferating CD8+CD39+ cancer-specific T lymphocytes and a decrease in the frequency of CD4+FoxP3+ Treg cells following infusion of GFP+Olfr644−/− and GFP+Vmn2r29−/− macrophages." (PMID 40588561, 2025).
cancer (continued). "Beyond Treg abundance alone, the intra-tumoral CD8+/FOXP3+ (or CD8+/Treg) ratio has shown a stronger prognostic and predictive value across cancers." (PMID 41394821, 2025). "Additionally, investigating the differential impact of FOXP3 loss in naive versus memory T cells could yield important insights, as memory T cells primed for defined antigens may particularly benefit from FOXP3 disruption, a strategy potentially valuable in settings of chronic infection and cancer." (PMID 40955316, 2025). "Our goal is to improve the outcomes of cancer immunotherapy by targeting FOXP3+ T-regulatory (Treg) cells with a next generation of antisense oligonucleotides (ASO), termed FOXP3 AUMsilence ASO." (PMID 39234236, 2024). "Although we focused on its role in mediating PD-L1 expression, FOXP3 clearly plays a more expansive role in regulating gene expression across a panel of immune- and EMT-related genes in cancer cells." (PMID 39099201, 2024). "The present candidate gene study focuses on the role of two X-linked genes, FOXP3 (Forkhead Box P3) and the PPP1R3F (Protein Phosphatase 1 Regulatory Subunit 3F), in PTC predisposition based on a priori biological hypothesis due to the described role of the selected genes in cancer predisposition." (PMID 39000267, 2024). "We also showed that FOXP3 induces other immune checkpoints as well as genes involved in EMT, promoting immune resistance and cancer metastases." (PMID 39099201, 2024). "Using the online tool GEPIA, we subsequently screened out four transcription factors (ETV4, FOXP3, E2F1 and XBP1) which are highly expressed in CRC and closely related to cancer." (PMID 38041531, 2024). "In most cancers, among T cells, VISTA is especially prevalent in FOXP3+ CD4+ Tregs, contributing to promoting their differentiation and maintaining their phenotype while suppressing effector T-cell function." (PMID 39684559, 2024). "In contrast, the densities of nTOB1+FOXP3+ Tregs, cTOB1+FOXP3+ Tregs, nTOB1+CD68+ macrophages, and cTOB1+CD68+ macrophages were higher in cancer tissues than in paracancerous tissues (P = 0.003, P < 0.001, P < 0.001, and P < 0.001, respectively)." (PMID 38617839, 2024). "As reported in previous studies, the density of CD8+ or FOXP3+ TILs can sharply reflect the immune status of TME and prognosis in patients with cancer." (PMID 38704243, 2024). "AZD8701, a first-in-class human clinical candidate antisense oligonucleotide (ASO) inhibitor targeting Foxp3, is currently being evaluated in Phase 1a/b clinical trials (NCT04504669) for its potential use in cancer treatment." (PMID 39290699, 2024). "Summarized, we demonstrate here that ICR High samples were indeed characterized by a high density of lymphocytes such as CD3+CD8-FoxP3- and CD3+CD8+ T cells, with these T cells being relatively proximal to cancer cells compared to CD3+FoxP3+ T cells." (PMID 38375478, 2024). "The density of FOXP3+ Tregs and CD68+ macrophages were relatively higher in cancer tissues than in paracancerous tissues (P = 0.002 and P < 0.001, respectively)." (PMID 38617839, 2024). "FOXP3, found on regulatory T cells, and IDO1 (macrophages and dendritic cells) are higher in cancer than precancers or controls (p < 0.0001, p < 0.0001)." (PMID 39672307, 2024). "To clarify this point, we evaluated expression of inflammatory cytokines in cancer samples, and found that mRNA expression of most of them were upregulated as a result of ASO FOXP3 targeting of Tregs." (PMID 39234236, 2024). "Spatial protein profiling corroborates these findings, revealing significantly decreased CD25+ and FOXP3+ Tregs in infiltrated stroma areas and CTLA4+ cells in both infiltrated stroma and carcinoma areas of GATA6high tumors." (PMID 38733987, 2024). "In vivo, the anti-PD-L1 antibody increased the number of dead CAFs and cancer cells, resulting in increased CD8+ T cells and decreased FoxP3+ regulatory T cells." (PMID 37668710, 2023).
cancer (continued). "Our data show that Tregs recognized by NEO-201 express a high percentage of Foxp3+/CD15s+ cells (average 66.14%), suggesting that NEO-201 can recognize highly suppressive Tregs in the peripheral blood of cancer patients." (PMID 36991390, 2023). "Higher expression of proteins associated with T cells, B cells, NK cells, and macrophages (such as GZMB, FOXP3, PD-1, CD20, CD56, and CD68) were observed in the ‘immune-rich cancer cell islets’ cf. ‘surrounding stromal leukocyte’ regions." (PMID 37046826, 2023). "We then aimed to investigate the prognostic value of COMP expression levels in CRC tumors corrected for PD-L1 expression by immune cells and cancer cells, and the different markers of immune cells populations (CD3+, CD8+, FoxP3+, CD68+, CD56+, and CD163+)." (PMID 37207219, 2023). "The mean number (±SD) of total Foxp3+ cells per HPF (high power fields) was 3.9 ± 6.2 in CMAs and 28.1 ± 33.8 in carcinomas CMCs." (PMID 36766393, 2023). "According to the density and distribution of FOXP3+ and CD8+ T cells etc, tumors can be classified as “hot” or “cold”, which can be used to predict the clinical outcome of various cancer patients." (PMID 35222387, 2022). "Taken together, the available research indicated that FOXP3, IRF3, CD274, and TP63 play an essential role in cancer, even in GBM." (PMID 35401877, 2022). "Pan-cancer analysis identified IKZF3, FOXP3, and JAK3 had a similar distribution and effects in HPV-associated HNSC." (PMID 35719936, 2022). "IL-2 has been shown to expand T effector cells for anti-microbial/anti-cancer immunity, while IL-2 can also induce or grow CD4+ CD25+ Foxp3+ regulatory T cells for immune regulation or tolerance." (PMID 35765887, 2022). "While Treg are generally assumed to have an immunosuppressive and thus adverse prognostic effect, there is ample evidence that high densities of intratumoural FoxP3+ T cells can be indicative of improved prognosis in CRC and other types of cancer." (PMID 35140715, 2022). "Tregs regulated by forkhead box P3 + (FOXP3 +), a forkhead helix transcription factor, are found in various tumors and are considered as a prognostic factor in human cancers." (PMID 36376881, 2022). "Tfr cells, generally defined as CXCR5+FOXP3+BCL6±ICOS± CD4+ cells, have been detected intratumorally in various cancers with limited assessments of their prognostic value." (PMID 36077836, 2022). "In a number of cancer types, including THCA, we observed that lower FOXP1, FOXP2 and higher FOXP3, FOXP4 levels in cancer tissues when compared with matched normal tissue." (PMID 36203616, 2022). "Patients in the stage III cancer cohort were shown to have increased CEA-specific CD8+ Teff cells and decreased FoxP3+ Tregs." (PMID 36159809, 2022). "Altogether, the protein expression analysis confirmed enrichment of FOXP3-positive cells in ALK-positive cancer and depletion of CD8-postive cells in EGFR-positive cancer." (PMID 34125345, 2022). "Tregs, which are typically characterized by an up-regulated expression of forkhead box P3 (FoxP3), are found in high proportions within the TME of most cancers." (PMID 36275816, 2022). "Results revealed a substantial decrease in cancer dimension, the most significant concentrations of IFN-γ and IL-17, and the slightest concentrations of HIF-1 alpha, MMP-2, MMp-9, IL-4, FoxP3, and VEGF the IT+IP+TEX-treated group." (PMID 35406692, 2022). "We also found that TSLP from cancers prepares the metastasis “soil”, such as inducing expression of CCL17 in the lungs to recruit CCR4+ cancer cells and their protector CCR4+FoxP3+ Tregs and Th2-skewed CD4+ T cells." (PMID 36104343, 2022). "FoxP3, another member of the FOXO family, is a major player in the immune system, and it consolidates cancer cell immunosuppression to anticancer drugs or cells." (PMID 36301031, 2022).